HP (haptoglobin)
Diseases named in the same sentence as HP in open-access papers (continued):
Sharing a sentence is not in itself a finding about the gene and the disease.
infection (continued). "Independent phase-variable expression has also been observed in genes involved in haemoglobin-haptoglobin acquisition which is hypothesised to provide an adaptive response to fluctuations in haem-iron availability/source influenced by the stage or site of infection." (PMID 40444152, 2025). "Haptoglobin, SAA, and LBP are APP and can bind bacterial endotoxins and are used to evaluate systemic responses to infection, inflammation, or trauma." (PMID 40202033, 2025). "Acute-phase proteins such as SAA3, M-SAA3.2, HP, and PTX3 are also upregulated, reflecting the localized expression of systemic responses to infection and tissue damage." (PMID 41156687, 2025). "While the number of significantly upregulated genes decreases to 37, these genes (e.g., ISG15, IFI6, IFI44L, HP, OAS1, IFI44, OASL, and IFI27) likely play a crucial role in the response to the progressing infection." (PMID 39282474, 2024). "The most highly infection-regulated proteins in the resistant line were hepcidin, CC chemokine, SAA, troponin, and haptoglobin (XP_021441697.1)." (PMID 37928534, 2023). "Of the top 20 contributing proteins for each infection identified by machine learning, 6 were found to be common to both LD and WNV (APOD, C4BPB, C7, HP, ITIH3, PGLYRP2), but with varying degrees of importance in each disease." (PMID 36569838, 2022). "Haptoglobin was increased, whereas albumin and PON-1 showed a decrease in experimentally infected cattle, and peaks were detected during the first month post-infection." (PMID 34551803, 2021). "Two APPs, serum amyloid A (SAA) and haptoglobin (HP), have previously been investigated in response to EEHV1 infection." (PMID 34793450, 2021). "Haptoglobin, albumin, PON-1 and ADA were identified as the biomarkers that showed changes of higher magnitude in the acute phase of the infection, whereas high total protein and globulin values were found in chronically infected cattle." (PMID 34551803, 2021). "Liver samples were collected approximately 7 d prior to infection and then on day 10 post-infection and evaluated for gene expression of the inflammatory cytokines IL-6 and TNF-α, and the acute-phase protein haptoglobin." (PMID 34673945, 2021). "In simultaneous infection and treatment, 10, 20 and 30 μM CCM decreased intracellular HBV by 33%, 46% and 54% respectively, while CsA and HP decreased the HBV viral load by 64% and 54% respectively." (PMID 34580340, 2021). "Haptoglobin, albumin, PON-1 and ADA were identified as the most promising biomarkers for the acute phase of the infection." (PMID 34551803, 2021). "In ruminants, haptoglobin (Hp) and serum amyloid A (SAA) are known to be the major positive acute-phase proteins increasing in relation to trauma, infection, stress, or neoplasia." (PMID 33092108, 2020). "Haptoglobin, a plasma protein that binds CFH and increases its clearance, minimizes the toxic effects of longer-stored RBCs during infection and is a biologically plausible novel approach to treat septic shock." (PMID 38362479, 2020). "In conclusion, the HSV-1 HP complex, in addition to the ssDNA binding protein ICP8, is sufficient to induce AAV replication in a transient infection." (PMID 32575422, 2020). "Addition of the HSV-1 helicase–primase complex (HP; UL5/ UL8/ UL52) and the single-strand DNA binding protein ICP8 (gene UL29) is sufficient to restore AAV progeny production in a transient AAV-infection model." (PMID 32575422, 2020). "In sentinels, we recorded large variation in lysis (and in haptoglobin and natural antibodies) both at baseline and after LPAIV exposure, which is likely due to individual variation in infection history." (PMID 33329501, 2020). "The differential regulation of immunity-related proteins such as haptoglobin may be one adaptation during hibernation that allows mammals to remain in their hypometabolic and hypothermic state, while aiding in the maintenance of immune competence and resistance against infections and diseases." (PMID 31649120, 2019).
infection (continued). "Eight plasma proteins, including APOA4, haptoglobin, MBL1, vWF, LBP, and sCD14, were affected 6 h after infection." (PMID 31803186, 2019). "Haptoglobin, a positive APP, increases in concentration according to deteriorated health status, infection, inflammation or trauma." (PMID 26610577, 2015). "The aim of this study was to investigate the innate immune response to infection with FMDV in cattle by measuring systemic levels of acute phase proteins SAA and HP as well as the biological activity of type 1 IFN in serum." (PMID 21592356, 2011). "The host response to infection was investigated through measurements of the concentrations of the acute phase proteins (APPs) serum amyloid A (SAA) and haptoglobin (HP), as well as the bioactivity of type 1 interferon (IFN) in serum of infected animals." (PMID 21592356, 2011). "Since AGP concentrations remain raised for longer after infection than other acute phase proteins such as CRP and haptoglobin, AGP has been used as a marker of sub-clinical infection in large scale human studies." (PMID 20042096, 2009). "Haptoglobin and SAA increased in the post-infection period, returning to normal after 2 weeks while AGP increased more slowly and remained elevated for 4 weeks p.i.." (PMID 18093286, 2007). "An acute phase protein, haptoglobin non-specifically increases in response to inflammation, infection or stress." (PMID 41012823, 2025). "Haptoglobin (Hp) is an APP that is widely accepted as a biomarker for systemic inflammation, and is released into the bloodstream in response to tissue damage, inflammation, infection, and bacterial components, as well as stress." (PMID 37104431, 2023). "In addition, neither the ETEC challenge nor the intervention approaches used in this study induced an APP response of haptoglobin, CRP, and MAP, which is generally triggered as a result of infection by pathogens." (PMID 38143275, 2023). "However, the haptoglobin concentration in FMT calves was modest when compared with other studies, where dairy calves were challenged with an infection (Haptoglobin = 1.23 g/L) or suffer mild diarrhea (Haptoglobin = 0.35 g/L)." (PMID 34573670, 2021). "Pre-treatment concentrations of IL-6 and NEFAs were elevated (p = 0.0005 and p = 0.0334, respectively), whereas haptoglobin concentrations were decreased among those animals that survived the infection, compared to those that did not (p = 0.0181)." (PMID 34073753, 2021). "In the presence of an infectious agent, leucocytes and epithelial cells produce chemoatractants, cytokines (e.g., IL-8, IL-1, TNF-α) and acute phase proteins (e.g., haptoglobin [Hp], serum amyloid A [SAA]), that attract neutrophils to the site of the infection." (PMID 31417901, 2019). "The major acute phase proteins Alpha-1 antitrypsin (A1AT) members 1 and 3, Haptoglobin, Hemopexin, Alpha-1 acid glycoprotein, CRP, and SAA2 reached comparable maximum fold change values at the common post-infection time-points between the infection types." (PMID 30774579, 2019). "Despite the markedly low levels of these protective proteins in children with CM or SMA, there were no observed differences in either haemopexin or haptoglobin levels between children who survived or died of the infection." (PMID 26691827, 2015). "Haptoglobin (Hp) being an APP, may increase in plasma in any inflammatory process like IV infection." (PMID 25888921, 2015). "Haptoglobin (HPR) expression is known to be increased in inflammation, infection, and cancer." (PMID 23372690, 2013). "Furthermore, only the WMS group displayed significantly elevated serum haptoglobin levels on both day 3 and 4 post-BHV-1 infection." (PMID 22435642, 2012). "The magnitude and the duration of the haptoglobin response was found to correlate well with the severity of clinical signs (fever) and with the extent of lung consolidation while SAA responded most rapidly to infection." (PMID 21430962, 2011).
infection (continued). "The plasma amounts of haptoglobin did not increase significantly for the breed most resistant to infection (Hampshire), though singular pigs displayed elevated haptoglobin levels." (PMID 19383119, 2009). "In addition, the concentration of cytokines and haptoglobin produced in vivo was measured in plasma and BALF at pre- and post-infection." (PMID 19383119, 2009). "Indeed, we observed a peak of haptoglobin in the swIAV group at 4 days post-swIAV infection as previously shown, but not in the PRRSV/swIAV group." (PMID 34834975, 2021). "Serum blood analysis of CRP as well as haptoglobin yielded no signs of infection or inflammation." (PMID 22718044, 2012). "Transferrin fluctuation further indicates systemic involvement, while the lack of significant changes in other proteins such as haptoglobin or α1-antitrypsin may reflect the nonestablishment of an acute infection or the early timing of sample collection relative to peak response." (PMID 40951670, 2025). "Only 3% of the piglets within the sample population had haptoglobin concentrations within the acute range of 3–8 mg/mL (PHASETM Haptoglobin Assay, Tridelta Development Limited, Maynooth, Ireland), suggesting acute infection or inflammation were likely absent in the majority of the piglets." (PMID 33282925, 2020). "Biochemistry data collected during the acute phase of infection shows a transitory and moderate increase of ASAT and haptoglobin levels in macaque model and no negative impact of antibody treatment on this marker." (PMID 37531329, 2023). "Viral particles, purified from the spent medium of either G. duodenalis HP or CAT isolates, were negative contrast stained and analysed by TEM before to carry out the experimental infection." (PMID 34201207, 2021). "Interestingly, both the pre- and post-infection feeding behavior patterns were more impacted in haptoglobin-responsive animals compared with the nonresponsive animals, suggesting lower haptoglobin responses may correlate with disease resiliency in feedlot cattle." (PMID 34673945, 2021). "In the V+H1N2var group, the mean concentrations in haptoglobin, IL-6, and TNF-α have not been changed as compared to the Control group either, but individual responses to the infection appeared to be heterogeneous, as shown by the large standard deviations." (PMID 33053905, 2020). "We found that most of the children with no infection (HP−/EBV−) and children with only EBV infection (HP−/EBV+) had a mild MN infiltration and no PMN in the gastric mucosa." (PMID 23638154, 2013). "During SARS-CoV-2 studies in non-human primates, we recently observed that haptoglobin levels, in comparison with CRP, had the same early increase 2 days after infection, but remained more consistently elevated for at least 10 days post-infection." (PMID 35327501, 2022).
cancer (120 papers, 1991 to 2026). A tumor composed of atypical neoplastic, often pleomorphic cells that invade other tissues. "We found that broadly across cancers, the HP genes exhibit elevated mutations, including copy number aberrations and differential gene expression in the tumor compared to healthy tissue, and are associated with patient survival." (PMID 41815548, 2026). "Diagnostic proteins associated with cancer growth included galactin-3 binding protein, testican-2, haptoglobin, Beta ig-h3, and protein AMBP." (PMID 36765599, 2023). "Altered glycosylation of the β chain of haptoglobin is a common theme in these studies, with increases in specific glycans associated with cancer progression." (PMID 37894372, 2023). "HP is the main glycoprotein in the acute phase response, and abnormal glycosylation is associated with several cancers and inflammatory diseases." (PMID 36505781, 2022). "It seems that in addition to the prevalence of specific haptoglobin genotype in some cancers regarding the geographical distribution of haptoglobin alleles in different parts of the world, the characteristics of the haptoglobin genotype is also efficacious." (PMID 31653132, 2019). "Studies have shown that there is a significant relationship between haptoglobin polymorphism and prevalence of some cancers." (PMID 31653132, 2019). "Haptoglobin also acts as an acute phase protein and has been associated with a variety of common disorders (e.g. cardiovascular disease, autoimmune disorders, malignancy)." (PMID 25889944, 2015). "The elevation of haptoglobin levels in these cancers may be linked to its ability to promote an inflammatory microenvironment that aids tumour progression." (PMID 40606553, 2025). "When analyzing HNC by cancer site, we found an increased risk of cancer in the lip and oral cavity per SD increase in haptoglobin (HR: 1.21; 95%CI: 1.14-1.29), platelets (HR: 1.12; 95%CI: 1.01-1.24), leukocytes (HR: 1.17; 95%CI: 1.08-1.28), and sedimentation rate (HR: 1.18; 95%CI: 1.02-1.35)." (PMID 37876941, 2023). "The aberrant glycosylation of haptoglobin is associated with many diseases, especially cancer." (PMID 36204290, 2022). "Furthermore, high circulating HP levels are associated with poor survival, demonstrating the clinical relevance of our findings for human cancer cachexia." (PMID 33142864, 2020). "Although the changes in the biological functions of the haptoglobin and Mac-2 bp with fucosylation remain unknown, the serum levels of these glycoproteins have potential as cancer/inflammation-associated biomarkers." (PMID 27002630, 2016). "Therefore, we propose that the tumor variant of haptoglobin undergoes both structural and post-translational changes that are advantageous to cancer cells during tumorigenesis." (PMID 25484625, 2014). "Haptoglobin-targeted therapies could offer a dual benefit in malignancies: one in reducing the oxidative stress associated with haemolysis in cancer patients and the other in mitigating the immunosuppressive effects of haptoglobin that facilitate tumour growth." (PMID 40606553, 2025). "In the human protein interaction network, HP genes cluster by the process type as well as with the known cancer driver genes." (PMID 41815548, 2026). "Modulating haptoglobin activity by enhancing its protective functions or inhibiting its pro-tumourigenic effects holds promise for improving cancer therapies." (PMID 40606553, 2025). "Ongoing research into haptoglobin’s role in cancer provides an exciting opportunity to develop therapeutic interventions that specifically modulate haptoglobin’s effects in the context of cancer, improving patient outcomes." (PMID 40606553, 2025). "In this prospect, we have exploited the reliability of our platform by detecting haptoglobin protein, which is relevant biomarker in numerous diseases such as hemolytic anemia, certain cancers, and inflammatory disorders." (PMID 39022532, 2024).
cancer (continued). "Here, we discuss some examples from the literature documenting how insight into HP PPI mechanisms can help cancer and pathogen-driven cancer research." (PMID 36910650, 2023). "Within the tumor, a very low haptoglobin level was found in tumors with poorly differentiated cancer, a condition with poor prognosis." (PMID 38201509, 2023). "Often protective mechanisms are more expressed in cancer patients in comparison to healthy individuals as found, for example, in ceruloplasmin, haptoglobin, hemopexin, and some protease inhibitors." (PMID 38201509, 2023). "Using the tandem mass tag (TMT) method, the authors showed that high levels of total and phosphorylated fibronectin 1 (FN1), haptoglobin (HP), S100A9, and fibrinogen α-chain (FGA) in EVs of CRC blood samples were associated with cancer progression." (PMID 37241967, 2023). "Haptoglobin is another relevant glycoprotein found to be a biomarker for different cancers, including esophageal, gastric, colon, gallbladder, pancreatic, prostate and ovarian." (PMID 34071388, 2021). "Haptoglobin is a conservative protein and is the subject of research as a potential biomarker of many diseases, including malignant neoplasms." (PMID 34207114, 2021). "Molecularly, it has also been shown that the two main proteins of Peroxiredoxin‐2 and Alpha‐1 antitrypsin were upregulated, and the expression of Haptoglobin protein was downregulated in cancer tissue." (PMID 32232956, 2020). "The increasing of haptoglobin in serum of patients with NSCLC was potentially useful in the clinical diagnosis of this cancer, especially in male subjects." (PMID 32232956, 2020). "In the present study the expression of two main proteins of Peroxiredoxin‐2 and Alpha‐1 antitrypsin were downregulated, while the expression of Haptoglobin protein was upregulated in the cancer tissue." (PMID 32232956, 2020). "We focused on three proteins: two down-regulated proteins (ceruloplasmin and C6) and one up-regulated protein (haptoglobin) because these proteins show significant p-value difference between cancer and healthy controls." (PMID 32620920, 2020). "It has been shown that haptoglobin genotype is related to the prevalence and progression of various types of cancer." (PMID 31653132, 2019). "One of the genetic factors that has been considered recently vis-à-vis the etiology of different cancers is the type of haptoglobin genotype." (PMID 31653132, 2019). "One of the genetic factors that has attracted much attention in recent years vis-à-vis various types of cancer is the type of haptoglobin genotype." (PMID 31653132, 2019). "Haptoglobin (Hp) is a major acute-phase protein, and its plasma concentration increases in response to inflammation, infection, and various cancers." (PMID 31034502, 2019). "In consonance with our study, several studies have shown that the specific genotype of haptoglobin has a higher prevalence in some cancers." (PMID 31653132, 2019). "Increased expression of sialyl Lewis antigens especially on tri- and tetra-antennary glycans has been reported on haptoglobin, alpha-1-acid glycoprotein and other acute phase proteins for inflammatory conditions as well as cancer." (PMID 30093973, 2018). "Elevated levels of serum haptoglobin were found in patients with inflammatory diseases and a variety of cancers, including lung cancer." (PMID 27248178, 2016). "Fucosylated haptoglobin (Fuc-Hpt) and Mac-2 binding protein (Mac-2 bp) are identified as cancer biomarkers, based on the results from a glyco-proteomic analysis." (PMID 27002630, 2016). "Our site-specific glycomic analysis revealed that both core fucose and Lewis types of fucose that is synthesized by other Futs expressed on haptoglobin, are increased in various cancers." (PMID 27136596, 2016). "The precise molecular mechanism for the function of haptoglobin in cancer pathogenesis is still unclear, by now." (PMID 27248178, 2016).